MCPH1 (microcephalin 1)
Diseases named in the same sentence as MCPH1 in open-access papers (continued):
Sharing a sentence is not in itself a finding about the gene and the disease.
Macrocephaly (2 papers, 2019 to 2022). Occipitofrontal (head) circumference greater than 97th centile compared to appropriate, age matched, sex-matched normal standards. "Brain growth disorders as micro- (ASPM, MCPH1) and macrocephaly (NFIX, GLI3) have been highlighted as relevant for the evolution in humans due to the impact in early brain development." (PMID 36550402, 2022).
Oral Squamous Cell Carcinoma (2 papers, 2013 to 2023). "The purpose of this study was to test if MCPH1 also functions as a TS gene using different approaches in OSCC (oral squamous cell carcinoma)." (PMID 23472065, 2013). "To test the possibility of MCPH1 as a TS gene, we first performed LOH study in a panel of 81 matched normal oral tissues and oral squamous cell carcinoma (OSCC) samples, and observed that 14/71 (19.72%) informative samples showed LOH, a hallmark of TS genes." (PMID 23472065, 2013).
osteosarcoma (2 papers, 2010 to 2011). A usually aggressive malignant bone-forming mesenchymal neoplasm, predominantly affecting adolescents and young adults. "For example, depletion of MCPH1 leads to lagging chromosomes and delayed cytokinesis in U2OS (osteosarcoma) cells." (PMID 21633703, 2011).
renal agenesis (2 papers, 2013). Renal agenesis (RA) is a form of renal tract malformation characterized by the complete absence of development of one or both kidneys (unilateral RA or bilateral RA respectively), accompanied by absent ureter(s). "In other MCPH subtypes, individual patients have been reported with short stature (especially in MCPH1 and MCPH5), early puberty, renal agenesis and polycystic kidneys." (PMID 23587236, 2013). "In addition, especially in patients with MCPH1 and MCPH5, early puberty, renal agenesis, and multicystic kidneys have been described." (PMID 24228726, 2013).
renal carcinoma (2 papers, 2020 to 2023). A carcinoma arising from the epithelium of the renal parenchyma or the renal pelvis. "Functional analysis in renal cancer cell lines demonstrated that over-expression of MCPH1/BRIT1 reduced proliferation, migration and invasion while increasing apoptosis supporting MCPH1/BRIT1’s role as a tumour suppressor gene in renal cancer." (PMID 36845691, 2023). "They found that all normal renal samples displayed positive MCPH1/BRIT1 staining while renal carcinoma tissues showed lower levels of MCPH1/BRIT1 staining compared to normal tissues." (PMID 36845691, 2023). "A study evaluated the expression of MCPH1/BRIT1 in 188 renal cancer and 20 normal renal tissues by immunohistochemistry." (PMID 36845691, 2023).
thyroid cancer (2 papers, 2020 to 2023). "Although high MCPH1/BRIT1 expression in a few cancers, oesophageal adenocarcinoma, renal papillary cell carcinoma, HCC, and thyroid carcinoma predicted reduced OS." (PMID 36845691, 2023).
anemia (1 paper, 2024). A reduction in the number of red blood cells, the amount of hemoglobin, and/or the volume of packed red blood cells. "Our findings on the mechanisms of the anemia developed by Mcph1 KO mice provide additional insight into the function of MCPH1 in fetal development, suggesting a critical role in the regulation of cytokinesis, a step required for cell proliferation." (PMID 38605277, 2024). "The report in Chk1-haploinsufficient mice of an hematopoietic disorder highly reminiscent of the one we evidenced in our Mcph1-KO mice, with multiple mitotic defects, increased binucleation, and frequent macrocytic anemia during their first year of life, supports this hypothesis." (PMID 38605277, 2024).
apical periodontitis (1 paper, 2025). "In turn, several lead SNPs of Necrosis of pulp or apical periodontitis may associate with tumour suppression (LRP1, CAMD2, MCPH1), while others are involved in plasma membrane structure, assembly, and transport." (PMID 40701953, 2025).
chronic kidney disease (1 paper, 2020). Impairment of the renal function secondary to chronic kidney damage persisting for three or more months. "However, to our knowledge no role for MCPH1 in acute or chronic kidney disease or vascular injury has been described." (PMID 32680471, 2020).
chronic lymphocytic leukemia (1 paper, 2023). "In addition, A study showed that downregulation of MCPH1/BRIT1 accompanied by loss of its promoter methylation resulted in upregulation of ANGP2 which is a crucial factor in tumour angiopoiesis in chronic lymphocytic leukemia." (PMID 36845691, 2023).
ciliopathies (1 paper, 2013). "However, Mcph1tm1a/tm1a mice did not display phenotypes normally associated with ciliopathies, such as situs inversus or renal cystic disease, suggesting that sufficient amounts of Mcph1 are available in the mutant for functional cilia formation in the majority of cells." (PMID 23516444, 2013).
colorectal cancer (1 paper, 2023). A primary or metastatic malignant neoplasm that affects the colon or rectum. "MCPH1/BRIT1 deletion, mutation and amplification have all been linked to colorectal cancer." (PMID 36845691, 2023). "The Kaplan–Meier curve shows that disease-free survival (DFS) is shorter in colorectal cancer patients with MCPH1/BRIT1 deletion than in patients with wild-type MCPH1/BRIT1 (P =0.025)." (PMID 36845691, 2023). "Cellulo analysis of these candidates (633 colorectal cancer patients), demonstrated that the deletion of MCPH1/BRIT1 resulted in the most significant increase in centriole number." (PMID 36845691, 2023). "Lack of heterozygosity (LOH) on chromosome 8p23.1, the MCPH1/BRIT1 locus has frequently been identified in advanced stage colorectal carcinoma patients, indicating the presence of a tumour suppressor gene." (PMID 36845691, 2023).
cutaneous melanoma (1 paper, 2023). A primary melanoma arising from atypical melanocytes in the skin. "Immunohistochemistry was performed identifying abnormal MCPH1/BRIT1 expression in 10% (1/10) of melanocytic nevi and in 86.3% (44/51) of primary cutaneous melanomas." (PMID 36845691, 2023). "The involvement of MCPH1/BRIT1 dysfunction was suggested in the development and progression of cutaneous melanoma." (PMID 36845691, 2023).
endometrial cancer (1 paper, 2023). Primary or metastatic malignant neoplasm involving the endometrium (mucous membrane that lines the endometrial cavity). "Mutations in MCPH1/BRIT1 were detected in 12% (5/41) of endometrial cancer indicating that MCPH1/BRIT1 could be a target gene of MSI." (PMID 36845691, 2023). "Mononucleotide microsatellite tracts of 14 genes of the DSB repair system including MCPH1/BRIT1 were analyzed in a series of 41 endometrial cancers with MSI." (PMID 36845691, 2023).
epilepsy (1 paper, 2022). A brain disorder characterized by episodes of abnormally increased neuronal discharge resulting in transient episodes of sensory or motor neurological dysfunction, or psychic dysfunction. "In all our cases these genes entered the region of deletion, but only Case 1 had seizures, which prevents us from coming to a conclusion of the main contribution of the CLN8 and/or MCPH1 genes in the formation of epilepsy." (PMID 35327368, 2022).
epithelial dysplasia (1 paper, 2013). "In the present study, we have carried out for the first time a comprehensive analysis to test if the MCPH1 gene functions as a tumor suppressor in OSCC, using a total of 91 OSCC samples, 2 epithelial dysplasia cases and 5 cancer cell lines." (PMID 23472065, 2013).
Ewing sarcoma (1 paper, 2020). A small round cell tumor that lacks morphologic, immunohistochemical, and electron microscopic evidence of neuroectodermal differentiation. "Another example is the detection of germline P/LP variants in MCPH1, which encodes a DNA damage response protein in three of our Ewing sarcoma patients." (PMID 32371905, 2020).
gastric cancer (1 paper, 2023). A primary or metastatic malignant neoplasm involving the stomach. "Another study characterising long non-coding RNAs (lncRNA) in gastric cancer identified over-expression of 6 key lncRNA including MCPH1/BRIT1 antisense RNA 1 (CTD-2541M15) which were associated with invasion and metastasis." (PMID 36845691, 2023). "Similarly, investigation of MCPH1/BRIT1 frameshift mutations in gastric cancer found that 11% (4/34) of cases with high MSI contained MCPH1/BRIT1 frameshift mutations compared to (0/45) with low MSI." (PMID 36845691, 2023).
glioma (1 paper, 2023). A benign or malignant brain and spinal cord tumor that arises from glial cells (astrocytes, oligodendrocytes, ependymal cells). "In contrast, it was found that the expression of MCPH1/BRIT1 did not alter during glioma development." (PMID 36845691, 2023).
Hearing impairment (1 paper, 2013). A decreased magnitude of the sensory perception of sound. "In the present study, microcephalin 1 (Mcph1)-deficient (Mcph1tm1a/tm1a) mice were found to exhibit hearing impairment as a part of the Sanger Institute's Mouse Genetics Project (MGP)." (PMID 23516444, 2013). "OM or hearing impairment has not been reported in human patients or mouse models with MCPH1 mutations previously." (PMID 23516444, 2013).
hepatocellular carcinoma (1 paper, 2023). A malignant tumor that arises from hepatocytes. "Scientists identified that MCPH1/BRIT1 deficiency is a potential factor in hepatocellular carcinoma (HCC) development." (PMID 36845691, 2023).
lung adenocarcinoma (1 paper, 2023). A carcinoma that arises from the lung and is characterized by the presence of malignant glandular epithelial cells. "The expression of MCPH1/BRIT1 varied among different histological subtypes, patients with lung adenocarcinoma expressed higher MCPH1/BRIT1 than patients with squamous cell lung carcinoma." (PMID 36845691, 2023).
macrocytic anemia (1 paper, 2024). Anemia that is characterized by increased red blood cell volume. "Our research revealed that Mcph1-knockout mice exhibited congenital macrocytic anemia due to impaired terminal erythroid differentiation during fetal development." (PMID 38605277, 2024).
non-small cell lung carcinoma (1 paper, 2023). A group of at least three distinct histological types of lung cancer, including non-small cell squamous cell carcinoma, adenocarcinoma, and large cell carcinoma. "Additionally, MCPH1/BRIT1 is an inclusion eligibility criterion in 2 clinical trials for squamous cell lung carcinoma, 3 clinical trials for non-small cell lung carcinoma, and 5 clinical trials for small cell lung carcinoma." (PMID 36845691, 2023).
oral cancer (1 paper, 2013). "Both HeLa and oral cancer cell lines are epithelial, meaning that overexpression studies conducted in KB cells may mimic the changes that MCPH1 would cause in oral epithelial cells." (PMID 23472065, 2013). "We have shown for the first time that MCPH1, being a tumor suppressor gene, is regulated by miR-27a in oral cancer and uses both of its target seed regions in its 3′-UTR." (PMID 23472065, 2013). "Since we did not correlate the expression levels of MCPH1 and CASP3 in OSCC samples, we performed a literature search to find if CASP3 expression has been reported in oral cancer." (PMID 23472065, 2013).
otitis media (1 paper, 2013). Inflammation of the anatomical structures of the middle ear, which is most often caused by an infectious process. "Expression of Mcph1 in the epithelial cells of middle ear cavities supported its involvement in the development of otitis media." (PMID 23516444, 2013). "We found expression of Mcph1 in the epithelia lining the middle ear consistent with its involvement in otitis media." (PMID 23516444, 2013).
ovarian tumours (1 paper, 2021). "Mcph1-ΔBR1 mice (both male and female) are infertile; however, almost all female mutants develop ovary tumours." (PMID 33542216, 2021). "Intriguingly, both Mcph1-ΔBR1 and Mcph1-Δ female mice developed high incidence of ovary tumours in a period of 18 months (27 and current study)." (PMID 33542216, 2021).
prostate adenocarcinoma (1 paper, 2023). "Bioinformatics analysis performed on TCGA datasets to identify centrosome genes associated with centrosome amplification and cancer development found that prostate adenocarcinoma cases with MCPH1/BRIT1 gene deletion demonstrated a worse OS and DFS." (PMID 36845691, 2023).
renal cell carcinoma (1 paper, 2020). "Mutations in the MCPH1 gene have been associated with diseases of neurogenesis and renal cell carcinoma." (PMID 32680471, 2020).
renal clear cell carcinoma (1 paper, 2023). "This review also showed that deregulation of MCPH1/BRIT1 is significantly associated with reduced overall survival in 57% (12/21) and relapsed free survival in 33% (7/21) of cancer types especially in oesophageal squamous cell carcinoma and renal clear cell carcinoma." (PMID 36845691, 2023).
testis atrophy (1 paper, 2021). "Similar to Mcph1-ko22 and Mcph1-Δ23 mice, Mcph1-ΔBR1 mice were infertile, with males showing testis atrophy without mature sperms due to block of meiosis and females lacking overt ovary structures." (PMID 33542216, 2021).
ZIKV infection (1 paper, 2021). "Dysregulation of the neuronal genes, such as RBBP8, ASPM, AXL, TBR2, MCPH1, and CENPF upon ZIKV infection may cause different neurological or brain development related disorders." (PMID 33891593, 2021).
tumor (32 papers, 2010 to 2026). "Overall, the loss of MCPH1 expression plays a key role in promoting genome instability and mutations, supporting its function as a tumor suppressor gene." (PMID 39885205, 2025). "This study also reported that increased MCPH1/BRIT1 cytoplasmic levels were associated with tumour grade (P =0.010)." (PMID 36845691, 2023). "Again, low MCPH1/BRIT1 expression was statistically associated with high grade tumours and advanced stage tumours." (PMID 36845691, 2023). "Frequent deletions and methylation of MCPH1 were reported in many cancers, including BC, and were also associated with tumor stages in BC." (PMID 33809336, 2021). "Further, reduced expression or depletion of MCPH1 has been linked to CA, mitotic errors, metastasis, higher tumor grade and stage, and worse patient outcomes." (PMID 32681070, 2020). "As TS genes show somatic mutations in tumor samples, the entire coding region and intron-exon junctions of the MCPH1 gene were sequenced in 15 OSCC samples and five cancer cell lines (viz., A549, HeLa, KB, SCC084 and SCC131)." (PMID 23472065, 2013). "Moreover, MCPH1 levels were depleted in 93 of 319 cases (29%) of BC associated with high tumour grade and TNBC phenotype and identified as an independent predictor of overall BC‐specific survival." (PMID 39775836, 2025). "Total depletion of MCPH1 has also been reported to lead to chromosomal aberrations in mammary epithelial cells, and experiments in mice show that MCPH1 deficiency results in increased chromosomal aberrations and promotes long-latency tumor formation." (PMID 26820313, 2016). "MCPH1, Microcephalin I, encodes a DNA damage response protein and is a potential tumour suppressor." (PMID 25148247, 2014). "Microcephalin-1 (MCPH1) is a tumour suppressor protein that regulates homologous recombination repair (HRR) and is down-regulated in several tumour types." (PMID 41931484, 2026). "This multi-level validation confirms the biological relevance of our prognostic signature and identifies MCPH1 as a potential novel tumor suppressor in MM." (PMID 41403951, 2025). "Regarding genomic stability and tumorogenesis, several reports have shown that MCPH1 overexpression decreases cellular proliferation, and cell migration, and induces cell apoptosis, indicating its tumor suppressor activity." (PMID 39885205, 2025). "Tumor-suppressor genes, including APC, BARD1, HMMR (RHAMM), KLLN, LZTR1, MCPH1 (BRIT1), MLH1, NF1, RB1CC1 (FIP200), SLC22A18, and SPTBN1, have been found to increase the risk of disease and tumor development." (PMID 40941673, 2025). "The percentage of tumour cells exhibiting positive nuclear MCPH1 staining was evaluated relative to the total number of tumour cells." (PMID 39775836, 2025). "MCPH1 plays a significant role in BC, with reported reduced levels in 17 of 54 cases (32%) of BC cell lines, suggesting its role as a tumour suppressor gene." (PMID 39775836, 2025). "All of these studies point to the possibility that MCPH1/BRIT1 functions as a tumour suppressor in the lungs." (PMID 36845691, 2023). "A common finding of this study is that the loss of MCPH1/BRIT1 gene expression plays a key role in promoting genome instability and mutations supporting its function as a tumour suppressor gene." (PMID 36845691, 2023). "MCPH1/BRIT1 over-expression in oral squamous KB cells reduced proliferation, cell invasion and anchorage-independent growth and tumour growth in nude mice." (PMID 36845691, 2023). "Given the role of MCPH1 in cell cycle regulation and DNA repair, its possible role as a tumor suppressor has been considered extensively." (PMID 35456440, 2022). "Another tumor suppressor, microcephalin 1 (MCPH1), from which we identified six selected-against alleles, acts as G2/M checkpoint and promotes apoptosis in response to DNA damage." (PMID 34059054, 2021). "MCPH1 deep gene deletions are seen in 5–15% of human cancers, depending on the anatomic site of the tumor." (PMID 32681070, 2020).